ASXL1 (ASXL transcriptional regulator 1)
Diseases named in the same sentence as ASXL1 in open-access papers (continued):
Sharing a sentence is not in itself a finding about the gene and the disease.
myelodysplastic syndrome (82 papers, 2010 to 2025). A clonal hematopoietic disorder characterized by dysplasia and ineffective hematopoiesis in one or more of the hematopoietic cell lines. "U2AF1 mutations and ASXL1 alterations are present in approximately half of myelodysplastic neoplasms (MDS) patients with isolated 20q deletion [del(20q)]." (PMID 37403747, 2023). "The ASXL1 is a member of the Polycomb group of proteins, and mutations in ASXL1 were shown to be associated with myelodysplastic syndromes and chronic myelomonocytic leukemia." (PMID 36167633, 2022). "ASXL1 mutations are observed primarily in myelodysplastic syndromes, but they are also observed in colorectal and endometrial cancer." (PMID 34536950, 2021). "ASXL1 is frequently mutated in patients with different types of myeloid malignancies, including myelodysplastic syndromes (MDS), myeloproliferative neoplasms, chronic myelomonocytic leukemia, and AML with MDS-related alterations." (PMID 34627254, 2021). "In myeloid malignancies, OGT directly stabilizes ASXL1 by O-GlcNAcylation and drives myeloid differentiation associated with the pathogenesis of myelodysplastic syndrome (MDS)." (PMID 33726758, 2021). "Mutations in ASXL1 have been observed frequently in acute myelogenous leukemia and myelodysplastic syndromes and are associated with a worse outcome due to an aberrant hematopoiesis." (PMID 27429816, 2016). "ASXL1 mutations are detected in patients with myelodysplastic syndrome (MDS), primary myelofibrosis, CMML and acute myeloid leukemia." (PMID 26019984, 2015). "Mutations in the ASXL1 (additional sex combs like 1) gene were first reported in 2009 in myelodysplastic syndromes." (PMID 22436456, 2012). "ASXL1 is mutated in all types of malignant myeloid diseases, including myelodysplastic syndromes (MDS), myeloproliferative neoplasms (MPN), chronic myelomonocytic leukemia (CMML) and acute myeloid leukemia (AML)." (PMID 22436456, 2012). "In addition, SETBP1 mutations have been reported to drive leukemic transformation in ASXL transcriptional regulator 1 (ASXL1)-mutated myelodysplastic syndrome (MDS)." (PMID 35898891, 2022). "Initially reported in myelodysplastic syndrome (MDS), mutations in the ASXL1 gene have been identified across different myeloid malignancies, including AML." (PMID 36498870, 2022). "ASXL1 is one of the most mutated genes in leukemias and myelodysplastic syndrome (MDS) and is associated to poor prognosis in MDS patients." (PMID 29967688, 2018). "ASXL1 mutations are frequently found in myelodysplastic syndromes (MDS) and in AML but appear to be enriched in secondary AML, AML-MRC, and intermediate risk AML." (PMID 26239249, 2015). "The objective of the study was to determine the prognosis and risk factors for additional sex combs like 1 (ASXL1) mutations in patients with acute myeloid leukemia (AML) and myelodysplastic syndrome (MDS)." (PMID 38146893, 2023). "ASXL1 is altered in 4.42% of all cancers with colon adenocarcinoma, lung adenocarcinoma, breast invasive ductal carcinoma, acute myeloid leukemia, and myelodysplastic syndromes." (PMID 34536950, 2021). "Driver mutations, such as DNMT3A, TET2, and ASXL1, appear early in AML clones and in the myelodysplastic syndrome (MDS)." (PMID 33363031, 2020). "ASXL1 (additional sex combs like 1) is a gene that is mutated in a number of hematological neoplasms including Myelodysplastic Syndrome (MDS), Acute Myeloid Leukemia (AML), Myeloproliferative Neoplasms (MPN), Chronic Myelomonocytic Leukemia (CMML) and Chronic Myeloid Leukemia (CML)." (PMID 30222780, 2018). "Recently, we reported that Asxl1+/− mice develop myelodysplastic syndrome (MDS) or MDS and myeloproliferative neoplasms (MPN) overlapping diseases (MDS/MPN)." (PMID 27352931, 2016).
myelodysplastic syndrome (continued). "ASXL1 mutations are found in myeloproliferative neoplasms (MPN), myelodysplastic syndromes (MDS), chronic myelomonocytic leukemia (CMML) and acute myeloid leukemia (AML)." (PMID 22436456, 2012). "Isolated 20q deletion [del(20q)] is a recurrent favorable abnormality in myelodysplastic syndrome (MDS) and may cause deletion of the ASXL1 gene." (PMID 40047093, 2025). "Furthermore, future studies on other recurrent drivers of human preleukemia, such as ASXL1, would be important for a more comprehensive understanding of preleukemic hematopoiesis." (PMID 38116120, 2023). "CMML is characterized by sustained monocytosis and an overlap of myeloproliferative neoplasms (MPN) and myelodysplastic syndromes (MDS) resulting from a cumulative mutational landscape including TET2 (60%), SRSF2 (50%), ASXL1 (40%), and the oncogenic RAS pathway (30%) mutations." (PMID 35884612, 2022). "Mutations in U2AF1 and SRSF2 affect the spliceosome and are frequently found in antecedent hematological disorders, such as myelodysplastic syndrome (MDS) and myeloproliferative neoplasms (MPN), as well as are mutations in chromatin regulating genes ASXL1 and BCOR." (PMID 33509276, 2021). "Interestingly, an ASXL1 somatic mutation, V1092M, detected in one ATL patient has also been reported in myeloproliferative neoplasms (MPN) and myelodysplastic syndromes (MDS)." (PMID 26880370, 2016). "The carriers of somatic PIGA and BCOR/BCORL1 mutations show a lower risk of AA transformation to myelodysplastic syndrome (MDS), whereas myeloid driver lesions such as DNMT3A and ASXL1 mutations characterize the group with a higher risk of malignancy." (PMID 38646536, 2024). "ASXL1 is an epigenetic regulator and the mutations in ASXL1 gene often coexist with RUNX1 and SETBP1 mutations in myelodysplastic syndromes (MDS) and AML14." (PMID 38129572, 2023). "Studies have displayed that ASXL1 mutations have been found in patients with a variety of hematological malignancies, including MPN, myelodysplastic syndrome (MDS), acute myeloid leukemia (AML), and chronic myelomonocytic leukemia (CMML)." (PMID 33386934, 2021). "Mutations in ASXL1 and SETBP1 genes have been frequently detected and often coexist in myelodysplastic syndrome (MDS) and acute myeloid leukaemia (AML)." (PMID 30367089, 2018). "Significant sex differences exist in the genomic aberrations underlying disease pathology, including a higher prevalence of SF3B1, SRSF2, and ASXL1 mutations in males and DNMT3A mutations in females with clonal hematopoiesis indeterminate potential and myelodysplastic syndromes (MDS)." (PMID 39402216, 2024). "In contrast, myeloid malignancies– including chronic myelomonocytic leukemia (CMML), myelodysplastic syndromes (MDS), myeloproliferative neoplasms, and both secondary and de novo AML, exhibit a diverse genetic mutational landscape of which somatic variants of ASXL1 are frequently observed." (PMID 39614348, 2024). "Notably, the critical role of mutations in epigenetic regulators and splicing factors, such as ASXL1, SRSF2 and U2AF1, in impaired hematopoiesis and the development of myelodysplastic syndromes (MDS), was validated in preclinical and clinical studies." (PMID 37444441, 2023).
acute myeloid leukemia (75 papers, 2010 to 2026). Acute myeloid leukemia (AML) is a group of neoplasms arising from precursor cells committed to the myeloid cell-line differentiation. "Patients with ASXL1 mutation (p = 0.03) and the triple-negative MF (p < 0.001) had an increased risk of progressing to secondary acute myeloid leukemia." (PMID 40287867, 2025). "Although mutations in ASXL1 are well-established in hematological malignancies, such as acute myeloid leukemia (AML), its role in developmental processes, particularly in brain development, remains poorly characterized." (PMID 40276524, 2025). "Although genetic mutations in additional sex-combs-like 1 (ASXL1) are prevalent in acute myeloid leukemia (AML), their exact impact on the AML prognosis remains uncertain." (PMID 38807730, 2024). "These BOS-causing ASXL1 variants are also high-prevalence somatic driver mutations in acute myeloid leukemia." (PMID 37053013, 2023). "ASXL1 gene is known to be frequently mutated in all types of malignant myeloid diseases including chronic myelomonocytic leukaemia and acute myeloid leukaemia." (PMID 35444210, 2022). "Three studies reported ASXL1 mutations to be associated with shorter overall survival in chronic myelomonocytic and acute myeloid leukaemias." (PMID 35444210, 2022). "Following studies provided further evidence regarding the incidental and non-malignant significance of the persistence of DNMT3A, TET2 and ASXL1 mutations detectable by NGS after initial induction chemotherapy for acute myeloid leukemia (AML)." (PMID 33562056, 2021). "Among patients with U2AF1 gene mutations, those with ASXL1 mutations were prone to develop into acute myeloid leukemia, those with RUNX1 mutations had an increased risk of relapse, and those with TET2 mutations had higher 1-year survival rate." (PMID 33122737, 2020). "The ASXL1 gene is involved in chromatin modification and is mutated in up to 20% of myelodsyplastic syndrome cases and a smaller percentage of acute myeloid leukemias." (PMID 28835367, 2017). "Mutations in known tumor suppressors DNMT3A (p.G728D) and ASXL1 (p.E657fs), consistent with mutations of known consequence in acute myeloid leukemia, were identified." (PMID 25000259, 2014). "ASXL1 is one of the most frequently mutated genes in acute myeloid leukemia (AML) and retains adverse‐risk status in intensively treated cohorts according to 2022 European Leukemia Net (ELN) risk criteria." (PMID 40678951, 2025). "Most studies investigating effects of somatic ASXL1 variants are conducted in leukemic cell lines since these variants have been associated with acute myeloid leukemia (AML)." (PMID 35361921, 2022). "Somatic mutations of ASXL1 are frequently found in hematological malignancies, such as acute myeloid leukemia (AML), chronic myelomonocytic leukemia (CML), and MPN." (PMID 34502524, 2021). "Regarding the MPN/AML transformation, mutations in genes encoding epigenetics modifiers such as ASXL1, IDH1, IDH2, EZH2, and TET2 are associated with nearly 30% of secondary leukemia transformations and de novo acute myeloid leukemia." (PMID 29515972, 2018). "Acute myeloid leukemia (AML) with a normal karyotype (CN-AML), which accounts for 40–50% of AML cases, commonly presents with genetic mutations in ASXL1, MLL, DNMT3A, TET2, IDH1 and IDH2 genes, all of which have important roles in epigenetic regulation." (PMID 24202321, 2013). "Here, we present a case of a patient who underwent hematopoietic stem cell transplantation (HSCT) due to acute myeloid leukemia (AML) and developed from donor cells triple-negative (TN) myeloproliferative neoplasms with mutations in the ASXL1, SETBP1 and EZH2 genes." (PMID 39907609, 2025). "ASXL1 mutations are associated with disorders such as Bohring–Opitz syndrome (BOS), acute myeloid leukemia (AML), and embryonic developmental defects." (PMID 38791157, 2024).
acute myeloid leukemia (continued). "In acute myeloid leukemia patients, EZH2 mutations frequently co-occurred with CEBPA (67%), ASXL1 (50%), TET2 and RAD21 mutations (33% each)." (PMID 33845873, 2021). "The epigenetic regulator additional sex combs-like 1 (ASXL1) is an adverse prognostic factor in acute myeloid leukemia (AML)." (PMID 34627254, 2021). "According to published data, the presence of ASXL1 mutations and the absence of any driver mutation were linked to an increased risk of progressing to secondary acute myeloid leukemia in the current MF cohort." (PMID 40287867, 2025). "Overall, the pathophysiological alterations in human acute myeloid leukemia (AML) cells bearing ASXL1 mutations have not been explored systematically." (PMID 28697759, 2017). "Case presentation: In this study we described a patient who underwent hematopoietic stem cell transplantation due to acute myeloid leukemia and subsequently developed triple-negative myeloproliferative neoplasms with mutations in the ASXL1, SETBP1 and EZH2 genes 9 years later." (PMID 39907609, 2025). "Further research is warranted to elucidate the genetic predispositions that may facilitate the transformation of leukemic MPNs into acute myeloid leukemia (AML), with emphasis on genes such as ASXL1, IDH1, IDH2, and SRSF2, among others." (PMID 39682300, 2024). "In contrast, clones with ASXL1 and DNMT3A mutations are inclined to grow over time and are associated with a lack of response to immunosuppressive therapy, and with the evolution towards MDS/Acute Myeloid Leukemia (AML)." (PMID 36233062, 2022). "To address this, we study an epigene, Additional Sex Combs-like 1 (ASXL1), where truncating heterozygous variants cause Bohring-Opitz syndrome (BOS, OMIM #605039), a germline neurodevelopmental disorder, while somatic variants are driver events in acute myeloid leukemia (AML)." (PMID 39614348, 2024). "Non-driver mutations, such as those in ASXL1, EZH2, TET2, SRSF2, and IDH1/IDH2, have been found to exacerbate disease severity, accelerate progression, and increase the risk of transformation to acute myeloid leukemia (AML)." (PMID 39434124, 2024). "We sequenced ASXL1 gene mutations in 61 patients with AML‐MRC and 46 controls with acute myeloid leukemia without other specifications (AML‐NOS) to identify clinical, cytomorphologic, and cytogenetic characteristics associated with ASXL1 mutational status." (PMID 32216059, 2020). "Furthermore, the transcriptional regulator 1 (ASXL1), which is essential for myeloid differentiation, is stabilized by USP7 in acute myeloid leukemia (AML)." (PMID 33327527, 2020).
chronic myelomonocytic leukemia (45 papers, 2012 to 2025). A myelodysplastic/myeloproliferative neoplasm which is characterized by persistent monocytosis, absence of a Philadelphia chromosome and BCR/ABL fusion gene, fewer than 20 percent blasts in the bone marrow and blood, myelodysplasia, and absence of PDGFRA or PDGFRB rearrangement. "ASXL1 is mutated (deleted or truncated) at high frequencies in all forms of myeloid malignancy; it is associated with poor prognosis in patients with chronic myelomonocytic leukemia (CMML), MDS, myelofibrosis, and AML23,24." (PMID 30135719, 2018). "Heterozygous ASXL1 mutations that occur in earlier exons have been documented in primary chronic myelomonocytic leukemia samples, suggesting that this subset have true loss of one allele, and thus that haploinsufficiency also can contribute to the onset of hematologic malignancy." (PMID 31064769, 2019). "Monocytosis, defined by increased monocyte levels, is significant in Chronic Myeloid Leukemia and Chronic Myelomonocytic Leukemia (CML and CMML), with mutations in ASXL1 and NRAS contributing to disease progression." (PMID 41141324, 2025). "In the current study, we found that the expression of ASXL1 significantly decreased in the BMSCs of chronic myelomonocytic leukemia patients (CMML-BMSCs) compared with healthy donors (HD-BMSCs)." (PMID 29423272, 2018). "Here, we showed that BMSCs derived from chronic myelomonocytic leukemia patients had reduced expression of ASXL1, which impaired the maintaining cord blood CD34+ cell colony-forming capacity with a myeloid differentiation bias." (PMID 29423272, 2018). "ASXL1, additional sex comb-like 1, is recurrently mutated in a range of myeloid malignancies, including MDS, AML, and chronic myelomonocytic leukemia, and has been noted to be one of the most commonly occurring mutations in patients with clonal hematopoiesis and MDS." (PMID 34548471, 2021). "We evaluated the expression of BCL2 in bone marrow CD34+ cells from a cohort of MDS and chronic myelomonocytic leukemia patients with and without ASXL1 mutations." (PMID 34548471, 2021). "Mutation of ASXL1 has been reported in AML and chronic myelomonocytic leukemia (CMML) patients." (PMID 26880370, 2016). "A study among Hispanics from Puerto Rico living in California, diagnosed from 2009 to 2018 with chronic myelomonocytic leukemia (CMML), found a higher rate of mutated TET2 and wild ASXL1." (PMID 37196029, 2023). "Two patients with SETBP1-mutated and ASXL1-unmutated developed AML transformation, whereas two other patients with ASXL1-mutated and SETBP1-unmutated evolved into chronic myelomonocytic leukemia (CMML) in their study." (PMID 33822276, 2021). "Mutations involving epigenetic regulators (TET2~60% and ASXL1~40%) and splicing components (SRSF2~50%) are frequent in chronic myelomonocytic leukemia (CMML)." (PMID 26771811, 2016). "ASXL1 mutations occur frequently in MDS/MPNs, particularly chronic myelomonocytic leukemia (CMML) (~ 43–49% of patients) and juvenile myelomonocytic leukemia (JMML) (7–8%), frequently in MDS (15–21%), and occasionally in MPN (8–10%), AML (3–10%), and CHIP (< 4%)." (PMID 36068610, 2022). "We also searched for TET2, DNMT3A, ASXL1, EZH2, IDH1/2 and CBL gene families mutations, given their potential clinical importance in diseases closely associated with SM like primary myelofibrosis, chronic myelomonocytic leukemia (CMML) and others." (PMID 22905207, 2012). "With regard to HMT, TET2, DNMT3A and ASXL1 mutations have been reported to be associated with treatment response in MDS patients, but not in chronic myelomonocytic leukemia." (PMID 27419369, 2016).